CD44 (CD44 molecule (IN blood group))
Diseases named in the same sentence as CD44 in open-access papers (continued):
Sharing a sentence is not in itself a finding about the gene and the disease.
tumor (continued). "As described in our previous study, the P/C ratio of CD44 may be thought to represent the degree of CD44 expression that is up‐regulated on GSCs residing in the specific microenvironment of the tumor periphery in GBM." (PMID 33543833, 2021). "ChS cell cultures derived from patient biopsies were able to form tumor spheres in vitro and expressed several surface MSCs specific markers, such as CD44, CD105, as well as bone marrow stromal-1 antigen (Stro-1), which is a cell surface marker expressed by stromal elements in human bone marrow-1)." (PMID 33804155, 2021). "It was demonstrated that expression of CD44 isoforms in HNSCC is differently associated with advanced T stage, regional and distant metastasis, and radiation failure, which suggests an involvement of CD44 in HNSCC tumor cell proliferation and migration." (PMID 32588101, 2021). "It is reported that the expression of CD44 is lower in BLCA than in none tumor tissue and it is associated with TNM staging." (PMID 34482807, 2021). "Hence, CD44 provides a physical link between the extracellular matrix and transcription factors such as Oct4, Sox2, and Nanog that, in turn, regulate tumour cell function." (PMID 34831291, 2021). "Additionally, there was a positive correlation between CD44 and vimentin (a marker of EMT) expression level, and the levels of both CD44 and vimentin are associated with MEC tumor grade." (PMID 35048028, 2021). "Therefore, CD44 can be used as an independent predictor for tumor development and as effective therapeutic target." (PMID 34837915, 2021). "CD44 is a transmembrane glycoprotein expressed in a variety of cells such as embryonic stem cells, connective tissue, and bone marrow, and has shown to be involved in cell proliferation, migration, and tumor initiation." (PMID 34948786, 2021). "To some extent, we speculated SLC27A6 promoted NPC metastasis via increasing CD24 and CD44 positive tumor stem cells." (PMID 35047398, 2021). "Furthermore, our data demonstrated that the tumor suppressor microRNA-30c serves as another negative regulator of cCSC clustering and lung metastasis by targeting CD44 as well as its downstream effector EGFR." (PMID 33995681, 2021). "Based on the accumulated information in this review, anti-tumor therapies aiming at the simultaneous blocking of both TEVs-directed CD44 loading and TEVs release might substantially undermine tumor spreading." (PMID 33540535, 2021). "Therefore, we calculated the DEGs between CD44+ tumor cells and CD44- tumor cells and identified the Pearson's correlated genes in CD44+ tumor cells." (PMID 35187044, 2021). "Moreover, CD44 targeted NIR-PIT with PD-1 blockade therapy was more effective than single therapies in mouse homograft models including a minimally immunogenic tumor." (PMID 36405499, 2021). "Through the esterification of alpha-tocopherol succinate with hyaluronic acid, a novel amphiphilic compound was created for the tumour-targeted delivery system, exploiting the ability of hyaluronic acid to bind to the membrane receptor CD44, a protein overexpressed by tumour cells." (PMID 34279260, 2021). "Moreover, the morphological features of the CD44+ sorted CSCs were more homogenous and had a different appearance in comparison with the total tumor cells." (PMID 34205649, 2021). "Similarly, it was shown that subcurative radiation enhanced cell proliferation and increased MMP2 and CD44 expression beyond the tumor periphery." (PMID 33744285, 2021). "As a cancer stem cell marker, CD44 is closely relevant to tumor progression and metastasis." (PMID 35664989, 2021). "The role of CD44 in promoting tumor metastatic ability has been studied in different cancer types." (PMID 34439211, 2021). "Specifically, T cell populations from Osm−/− tumours expressed higher levels of the co-stimulatory molecule 4-1BB (T_C6), activation markers such as CD44 (T_C8 and T_C4) and CD127 (T_C13), alongside decreased levels of TCRβ (T_C5), consistent with improved T cell activation." (PMID 34921158, 2021).
tumor (continued). "Here, we assessed whether circulating tumor cells (CTCs) in peripheral blood can serve as a disease surrogate, focusing on CD44 and CD74 expression as prognostic markers for BM." (PMID 34209696, 2021). "Hyaluronic acid-modified NPs can interact with CD44 and receptors for hyaluronate mediated motility, which are overexpressed on the surface of a variety of tumor cells, while it also can be degraded by hyaluronidase around the tumor." (PMID 34654430, 2021). "To determine whether local delivery altered the differentiation of T-cells, we evaluated the expression of CD44 and CD62L tumor antigen-specific T-cells to identify differentiation into CD44+CD62- effector, CD44+CD62L+ memory, or CD44-CD62L+ naïve T-cells." (PMID 34194619, 2021). "The HA is selectively targeted by tumour cell receptors such as CD44." (PMID 35011272, 2021). "Bovine milk exosomes were modified with hyaluronic acid (HA), which targets CD44 overexpressed on tumors, and then loaded with Dox to form a new carrier (HA-mExo-Dox) that specifically targets CD44-positive tumor cells and allow tumor cells to efficiently take up Dox." (PMID 34142930, 2021). "For instance, we previously found miR-34a to be devoid in prostate cancer stem cell (PCSC) populations (e.g., those identified as CD44+/hi), and overexpression of miR-34a induced pronounced inhibitory effects on tumor growth and metastasis in vivo by negatively regulating PCSCs." (PMID 33763422, 2021). "CSCs also exhibit enhanced potential and efficacy to generate neoplasms, as approximately 100 CD44+/CD24− BCSCs injected orthotopically could result in tumor formation in the breast." (PMID 34831048, 2021). "In addition, hyaluronic acid (HA) was coated on the cerium’s surface to target CD44-overexpressing tumor cells, and natZr was chelated on the Fe3O4@CeO2 surface to show the usefulness of labeling the radioisotope 89Zr (T1/2 = 3.3 d)." (PMID 34577662, 2021). "EGFR enhances CD44-mediated tumor cell aggregation and CD44 stabilizes EGFR." (PMID 33995681, 2021). "But we know few about the immune functions of CD44 in tumor until now." (PMID 35187044, 2021). "Furthermore, injection of only 100 CD44+ cells is sufficient to initiate tumour formation in nude mice, and single CD44+ cells form tumour spheres with stem cell characteristics, which develop into tumours once inoculated into nude mice." (PMID 34680897, 2021). "Moreover, we found an increased population of activated CD44+ T cells in tumor and TNF-α producing effector CD4+ and CD8+T cells in the spleen." (PMID 33499256, 2021). "Understanding the mechanisms of CD44/HA interaction and activating the HA-induced antitumor effects in this population of cancer cells will be valuable when it comes to comprehending the stepwise mechanisms of the invasion in highly migratory tumor cells." (PMID 34770956, 2021). "OPN may directly regulate tumor cell proliferation, migration through binding to CD44 or the integrin receptors on tumor cell surface." (PMID 33670921, 2021). "The identification of additional genes that maintain and regulate the tumor-initiating properties of CD44+CD133+ Caco-2 cells might provide rational targets for therapeutic intervention." (PMID 33994850, 2021). "Notably, Kdm3a is highly expressed in Cd44 (a liver CSC marker)-positive hepatocytes, and it controls the number and tumor-initiating potential of Cd44-positive cells." (PMID 32354028, 2020). "Moreover, it is possible to carry out the phage display on cells pre-enriched for a certain tumor marker, for example, CD44 and CD133." (PMID 33396774, 2020). "CD44 expression is characteristic in cells under certain pathological conditions such as infarcted myocardium, infiltrating leukocytes, wound myofibroblasts, vascular cells, and many tumor cells." (PMID 32133350, 2020). "Ex vivo CD44-targeted NIR-PIT remarkably reduced CD44+ CD8 T cells isolated form tumor tissues." (PMID 32937841, 2020).
tumor (continued). "CD44 plays a crucial role in tumor progression, metastasis, and chemoresistance." (PMID 32434417, 2020). "Single-cell RNA sequencing of one PTEN-mutant tumor of a non-responder showed the association of the immunosuppressive signature (T regulatory cells, macrophages, microglia, neutrophils) with CD44 + tumor cells involved in invasion." (PMID 31376079, 2020). "CD44 could be described as a “bridge” that links tumor cells and platelets to help tumor cell arrest in circulation." (PMID 32943996, 2020). "Experimental evidence shows that CD44 is the most effective membrane protein to bind hyaluronic acid, thus HA has been extensively used in developing nanocarriers that demonstrate preferential tumor accumulation and increased cell uptake in cancer cells." (PMID 32349323, 2020). "CD44 plays a major role in modulating migration/invasion processes during tumour advancement." (PMID 32445177, 2020). "We clarified whether TAMRA-FP hotspots localize to tumor regions undergoing matrix remodeling using the stiffness markers pMLC2 and tenascin C along with HA and CD44." (PMID 32190011, 2020). "Moreover, both T‐cell populations displayed an increase in CD44 expression that correlated with a decreased CD62L expression in Cx3cr1‐Rheb1Δ/Δ compared to Rheb1fl/fl tumours." (PMID 32567735, 2020). "Notably, HA is more abundant in the GBM ECM than healthy brains while CD44 is often found to be upregulated in GBM tumours." (PMID 32366909, 2020). "We also examined CD44 expression in tumor-infiltrating CD8+ T cells in a MOC2-luc tumor." (PMID 33322807, 2020). "As CD44 acts as the receptor for HA which can drive cancer migration, expansion, and metastasis, blocking HA-CD44 interaction by the degradation of HA or competitive suppression of CD44 might be also a promising strategy for tumor management." (PMID 33303029, 2020). "To further determine whether caffeic acid treatment affects the stem cell-like properties of colorectal CSCs in vivo, we assessed the percentage of the CD44+ CD133+ subpopulation of tumor-xenograft-derived cells." (PMID 33425893, 2020). "Tumor cell CD44 is also involved in P-selectin binding, either directly or via fibrin." (PMID 33042789, 2020). "The abundant surface terminations in the Ti3C2 NSs also enabled functionalization for specific tumor targeting, such as hyaluronic acid coatings which increased colloidal stability and enabled active targeting of the surface protein CD44+ overexpressed in cancer cells." (PMID 32373222, 2020). "CD44 is instrumental in many physiological and tumor pathological processes." (PMID 32344833, 2020). "Interestingly, coincubationwith Exo-siCD44 significantly increased sensitivity to chemotherapy in MCF-7/ADR cells and tumor-bearing mice, thus suggesting that exosomal CD44 have an important role for the MCF-7 cells that acquired DOX resistance." (PMID 32760666, 2020). "Further, total CD44+ T cells which include both central memory (CD62Lhigh CD44high, P2) and effector memory (CD62Llow CD44high, P3) were also larger after the PD-1 blockade therapy over ctrl IgG treated group in the hosts with responsive tumor." (PMID 32122466, 2020). "Taken together, the data suggest that chemotherapy induces CD44 expression on TMPs and, as a result, may contribute to tumor cell aggressiveness." (PMID 33050539, 2020). "Similarly, CD44–hyaluronan interaction induces the expression of miR-10b, which upregulates RhoA and RhoC resulting in the cytoskeleton activation and increased tumor cell invasiveness." (PMID 33321819, 2020). "There is ample evidence for CD44 expression and signaling in the development of cancer therapy resistance and several publications in various tumor models demonstrate functional crosstalk between CD44 and STAT3 (signal transducer and activator of transcription 3)." (PMID 33335857, 2020). "FACS revealed a distinct population of CXCR4+MET+ cells in patient’s tumor which could be further sorted into CD44+ and CD44− cells." (PMID 32066735, 2020).
tumor (continued). "Similarly, human melanoma metastasis is lessened, animal survival in SCID mouse is enhanced, tumor growth reduced, and apoptosis commenced in murine breast tumors due to anti-CD44 antibodies." (PMID 32211043, 2020). "Next, studies were performed to determine whether CD44 had an impact on tumor cell growth rates in vivo." (PMID 32455980, 2020). "This is plausible as CD44/CD44v are considered CSC markers in several tumor types, including GC." (PMID 32252293, 2020). "CD44 expression is reduced in redirected cells and redirected cells lose tumor forming ability." (PMID 32774772, 2020). "CD44 is a well-known marker of CSCs and plays important roles in tumor initiation and development." (PMID 33303029, 2020). "The percentages of tumor-infiltrating CD8+CD44+ T cells were also confirmed by flow cytometry." (PMID 32733437, 2020). "The binding of HA to its predominant receptor, CD44, was shown in vitro and in vivo to interact with MMPs, thereby driving tumour progression and upregulation of the PI3K/AKT and ERK signalling pathways, inducing pro-migratory effects and apoptotic resistance in GBM." (PMID 32366909, 2020). "Of note, they demonstrated an additional mechanism of action of TLR2 activation, which was based on the TLR2/MyD88-mediated activation of the Wnt pathway, with the induction of the expression of its targets CD44 and Lgr5, which may lead to tumor initiation." (PMID 33321934, 2020). "Similarly, murine 4T1 breast cancer cells release soluble CD44, which in turn induces macrophage-mediated IL-1β production, leading to tumor growth and lung metastases." (PMID 32635472, 2020). "Additionally, CD44 proteins are involved in tumor pathological processes, including cell proliferation, angiogenesis, invasion, and metastasis." (PMID 32344833, 2020). "Another CD44 variant, CD44v3, binds to several heparan sulfate-binding growth factors such as fibroblast growth factors (FGFs) and heparin-binding epidermal growth factor (HB-EGF), and induces tumor progression." (PMID 33000243, 2020). "CD44 plays an important role in tumor cell initiation, proliferation, invasion and CSC properties." (PMID 32984031, 2020). "Moreover, CD44 and its CD44v isoforms are expressed as surface markers of cancer stem cells (CSCs), influencing key CSC-associated properties such as tumor initiation, self-renewal, metastasis and chemoresistance." (PMID 32252293, 2020). "Each of the CD44 isoforms has multiple biological functions in normal and tumor cells." (PMID 32344833, 2020). "However, since these factors were rarely reported in each study, we were unable to evaluate the potential prognostic role of tumor CD44 expression for survival according to these characteristics." (PMID 32232385, 2020). "Indeed, CD44 blockade with anti-CD44 antibody prevented the tumor formation and metastasis of CD44-positive hepatic CSCs in vivo." (PMID 32987767, 2020). "As an important stem cell marker of CSF‐CTCs, CD44 improves tumor initiation capacities of CTCs." (PMID 33377642, 2020). "Mechanistically, GAPLINC could serve as a decoy for miR-211-3p to restore the levels of cancer stem cell marker CD44, enhancing tumor progression." (PMID 32370770, 2020). "Initially, the patient with stemness gene amplifications had a high concentration of EpCam+CD44+CD24– tumor stem cells – more than 50%, while patient Ti41749/17 had a level slightly above 30% and a two-fold higher concentration of EpCam+CD44hiCD24– cells (37% compared with 18%)." (PMID 32523653, 2020). "Furthermore, in head and neck cancer, it was found that tumor cells expressing high levels of CD44 are less immunogenic than CD44lo cells." (PMID 32391048, 2020). "Knocking out CD44 in vivo and in vitro is beneficial in suppressing tumor metastasis." (PMID 32210805, 2020). "Substantial heterogeneity was measured between CD44 expression and tumor grade and T stage." (PMID 32434417, 2020).
tumor (continued). "In fact, CD44 variants such as CD44v6 and CD44v8-10 are overexpressed but not exclusively expressed by tumor cells." (PMID 31973075, 2020). "These initial findings clearly suggest that CD44 in non-tumor tissues is potentially associated with risk of tumor recurrence after hepatic resection for HCC." (PMID 32466488, 2020). "Examples of targeting moieties often exploited in nanomedicine are transferrin and folate, which target tumour cells overexpressing the corresponding receptors, or hyaluronic acid, which directs nanocarriers to CD44-overexpressing tumour cells, among many others." (PMID 32117671, 2020). "Finally, in ovarian cancer, TLR2 expressed on CD44+/MyD88+ CSCs promotes their self-renewal and induces the secretion of pro-inflammatory cytokines, thus actively contributing to tumor repair following injury induced by surgery or chemotherapy." (PMID 33321934, 2020). "Therefore, most of activated immune cells in tumor beds are eliminated immediately after CD44-targeted NIR-PIT." (PMID 32937841, 2020). "Co-staining against HIF-1α, a hypoxia marker, and CD44, a marker previously used to define perivascular and perinecrotic tumor areas, revealed that DLK1 localized prevalently in perivascular and hypoxic niches, with previously unreported nuclear localization specifically in these areas." (PMID 32205867, 2020). "These two important antitumor properties may be mediated by the abrogation of FASN and CD44 pro-tumor activity." (PMID 31936544, 2020). "CD44+/CD24−/low phenotype was associated with BRCA1+ and basal-like tumor status." (PMID 32316333, 2020). "After 8 days, new tumours were detected in the flanks of all four mice in the ALDH+CD44+ group." (PMID 32390009, 2020). "Although many studies have reported that the expression of CD44, CD44v, CD133, EpCAM and ALDH1A1 is associated with tumor progression and can be used to predict patient’s outcome, their prognostic significance in the recurrence of CCA in patients has not been elucidated." (PMID 32039729, 2020). "Since CD44 is also a surface marker of cancer stem cells (CSCs), the sphere forming assay, which functionally assesses the presence of a stem cell population and the capability of reinitiate tumor formation, was carried out." (PMID 33375053, 2020). "CXCR4+MET+CD44+ cells amounted to 2.2% of total tumor cells on average (range: 0.2–11%)." (PMID 32066735, 2020). "In gastric cancer, GAPLINC (Gastric Adenocarcinoma Associated, Positive CD44 Regulator, Long Intergenic Non-Coding RNA) is a HIF-1α direct, transcriptional downstream target, and could promote invasive tumor progression." (PMID 32370770, 2020). "Further research demonstrated that circIFI30 could function as a sponge for miR-520b-3p to promote cell proliferation, invasion, tumor growth and metastasis through up-regulating the expression of miR-520b-3p target gene CD44." (PMID 32497020, 2020). "Additionally, numerous targets of expressions which were observed in carcinogenesis and tumor progression were reported to be regulated by miR-34a, such as CD44, BCL2, NOTCH1, CDK4/6, MET, MYC, and many other molecules." (PMID 32391256, 2020). "Interestingly, although CD44 serves as a biomarker of tumor-initiating cells with high expression of CD44, overexpression of CD44 cannot endow low CD44-expressing cells with properties of tumor-initiating cells." (PMID 33303029, 2020). "Suppression of CD44-HA crosstalk results in the annulment of tumor cell motility." (PMID 31963556, 2020). "Taken together, these results suggested that CD44 cross-linking may regulate tumor cell migration and invasion by altering the phosphorylation of Moesin." (PMID 33292278, 2020). "Colony formation, transwell and tube formation assays were performed to assess whether FZD2 or CD44 knockdown could partly inhibit the tumour-promoting effect induced by LEF1-AS1 overexpression." (PMID 33292271, 2020).